PIGN (phosphatidylinositol glycan anchor biosynthesis class N)
Description:
Ethanolamine phosphate transferase that catalyzes an ethanolamine phosphate (EtNP) transfer from phosphatidylethanolamine (PE) to the 2-OH position of the first alpha-1,4-linked mannose of a 2-acyl-6-[alpha-D-mannosyl-(1->6)-alpha-D-mannosyl-(1->4)-alpha-D-glucosaminyl]-1-(1-radyl,2-acyl-sn-glycero-3-phospho)-1D-myo-inositol (also termed H3) intermediate to generate a 2-acyl-6-[alpha-D-mannosyl- (1->6)-2-phosphoethanolamine-alpha-D-mannosyl-(1->4)-alpha-D-glucosaminyl]-1-(1-radyl,2-acyl-sn-glycero-3-phospho)-1D-myo-inositol and participates in the eighth step of the glycosylphosphatidylinositol-anchor biosynthesis (By similarity). Also transfers the EtNP on a mannosyl GPI intermediate, 2-acyl-6-(alpha-D-mannosyl-(1->4)-alpha-D-glucosaminyl)-1-(1-radyl,2-acyl-sn-glycero-3-phospho)-1D-myo-inositol (also termed H2) (By similarity). May act as suppressor of replication stress and chromosome missegregation.
Synonyms: GPI-ETI; PIG-N; MCD4; MCAHS; MCAHS1; MDC4
Tractability: Antibody: its Gene Ontology location is reachable by antibodies, with high confidence; UniProt predicts a signal peptide or a membrane-spanning region; the Human Protein Atlas places it where antibodies can reach. PROTAC: ubiquitination databases record sites on it; its protein half-life has been measured.
Gene: Protein-coding gene on chromosome 18 (61,905,255 to 62,187,118, reverse strand). Ensembl gene ENSG00000197563.
Subcellular location: Endoplasmic reticulum membrane
Subcellular location (Human Protein Atlas): Cytosol; Plasma membrane
Pathways (Reactome):
Metabolism of proteins: Synthesis of glycosylphosphatidylinositol (GPI)
Gene Ontology:
Molecular function: mannose-ethanolamine phosphotransferase activity; transferase activity
Biological process: GPI anchor biosynthetic process
Cellular component: cytosol; membrane; plasma membrane; endoplasmic reticulum membrane
Genetic constraint (gnomAD): Loss-of-function variants: 25 observed, 23.91 expected, observed/expected ratio (o/e) 1.05, 90% interval 0.76 to 1.46. The upper end of that interval is the gene's LOEUF score, 1.46, which puts it in group 6 of 6, group 1 being the genes least tolerant of losing a copy. Missense variants: 356 observed, 371.59 expected, observed/expected ratio (o/e) 0.96, 90% interval 0.88 to 1.05. Synonymous variants: 133 observed, 135.64 expected, observed/expected ratio (o/e) 0.98, 90% interval 0.85 to 1.13.
Gene-disease validity (ClinGen):
ClinGen rates the evidence that PIGN causes each of these diseases.
multiple congenital anomalies-hypotonia-seizures syndrome 1 (autosomal recessive): Definitive. Any multiple congenital anomalies/dysmorphic syndrome-intellectual disability in which the cause of the disease is a mutation in the PIGN gene.
Homologues: Orthologues: chimpanzee PIGN (99% identical), macaque PIGN (98% identical), rabbit PIGN (91% identical), guinea pig PIGN (88% identical), mouse Pign (87% identical), dog PIGN (86% identical), rat Pign (83% identical), pig PIGN (80% identical), tropical clawed frog pign (67% identical), zebrafish pign (62% identical), Caenorhabditis elegans pign-1 (34% identical), Drosophila melanogaster PIG-N (31% identical), and 4 more.
Diseases named in the same sentence as PIGN in open-access papers:
PIGN is named in the same sentence as 59 diseases in open-access papers, as found by Europe PMC text mining. Sharing a sentence is not in itself a finding about the gene and the disease. The quoted sentences say what the papers report.
developmental delay (6 papers, 2017 to 2025). "Mutations in PIGN can lead to visceral abnormalities (>90%), psychomotor developmental delay (100%), hypotonia (100%), and seizures (93%)." (PMID 40099311, 2025). "As PIGN is expressed in many tissues, several body systems are affected by mutations in this gene, leading to severe developmental delay." (PMID 33193741, 2020). "In contrast to the developmental delays and early mortality seen in humans and mice, respectively, with loss of PIGN function, the first episodes of dyskinesia occurred in young-adult dogs." (PMID 27891564, 2017). "This includes severe brain malformations, mental retardation, seizures, psychomotor developmental delay, and cardiac, urinary, and gastrointestinal abnormalities (the associated genes are: DNML, CEP290, CASK, PIGN)." (PMID 36421828, 2022). "In contrast, a child with likely hypomorphic compound heterozygous missense PIGN mutations showed no dysmorphic features, moderate developmental delay, and a later onset of seizures and spastic quadriparesis." (PMID 27891564, 2017).
Fryns syndrome (6 papers, 2019 to 2025). Fryns syndrome (FS) is a multiple congenital anomaly syndrome characterized by dysmorphic facial features, congenital diaphragmatic hernia, pulmonary hypoplasia, and distal limb hypoplasia, in addition to variable expression of additional malformations. "Inherited PIGN mutations have been associated with multiple congenital anomalies-hypotonia-seizures syndrome and Fryns syndrome, with some mutations related to milder forms of clinical presentation." (PMID 40064858, 2025). "A homozygous missense variant in PIGW (c.[106 A>G];[106 A>G], p.(R36G) that segregated in both fetuses was prioritized because phenotypes caused by variants in PIGV and PIGN genes of the PIG family show a phenotypic overlap with Fryns syndrome or are described to be causal for the Fryns phenotype." (PMID 30679815, 2019). "For example, the majority of patients with multiple congenital anomalies hypotonia and seizures, type 1 (MCAHS1; MIM 614080) and Fryn syndrome (MIM 229850), resulting from biallelic PIGN variants, do not demonstrate hyperphosphatasia." (PMID 38790248, 2024).
epilepsy (5 papers, 2022 to 2025). A brain disorder characterized by episodes of abnormally increased neuronal discharge resulting in transient episodes of sensory or motor neurological dysfunction, or psychic dysfunction. "Another gene upregulated, albeit minimally altered in expression, the role of PIGN is in anchoring proteins to blood cells, and mutations in the gene have been linked to various epilepsy phenotypes including generalized seizures in children." (PMID 39596674, 2024). "Given that mutations in the PIGN gene may be an underrecognized cause of epilepsy, this case report aims to highlight the importance of early diagnosis of this condition." (PMID 40099311, 2025). "This is a rare autosomal recessive genetic condition caused by a PIGN gene mutation, presenting with GDD, hypotonia, and epilepsy." (PMID 40099311, 2025). "The diagnosis of PIGN mutations is primarily based on the patient’s clinical presentation, including GDD, hypotonia, and epilepsy." (PMID 40099311, 2025). "The CFA14 risk haplotype was associated with upregulation of CLIC1, ACE2, and PIGN and downregulation of EPDR1, all known to be involved with epilepsy or the Wnt/β-catenin signaling pathway." (PMID 39596674, 2024). "Patients with epilepsy from diverse ethnic backgrounds should be evaluated for MCAHS1 or PIGN mutations, as these may be responsible for PIGN-related epilepsy." (PMID 40099311, 2025).
COVID-19 (4 papers, 2021 to 2024). A disease caused by infection with severe acute respiratory syndrome coronavirus 2. "Among these genes, CCR5 and PIGN were novel susceptibility genes for COVID-19." (PMID 34557504, 2021). "Moreover, the most recent study has revealed that GPI biosynthesis may be severely altered by SARS-CoV-2 replication, thus indicating PIGN as a novel risk gene for COVID-19." (PMID 36363484, 2022). "Two of these genes, CCR9 and CXCR6, were also found within the set of COVID-19 associated genes, while CCR5 and PIGN genes were novel." (PMID 34557504, 2021). "Together, our SMR analysis and TWAS of COVID-19 identified a total of 14 genes associated with COVID-19, comprising seven genes implicated by the input or previous GWASs and seven novel genes (including three protein-coding genes, CCR5, MAPT, and PIGN)." (PMID 34557504, 2021). "Together, our SMR and TWAS analyses identified three novel protein-coding genes for COVID-19, namely, CCR5, MAPT, and PIGN." (PMID 34557504, 2021).
Epileptic encephalopathy (3 papers, 2022 to 2025). A condition in which epileptiform abnormalities are believed to contribute to the progressive disturbance in cerebral function. "PIGN mutations cause epileptic encephalopathy and MCAHS1 (multiple congenital anomalies-hypotonia-seizures syndrome)." (PMID 37628788, 2023). "This is the first study to document developmental and epileptic encephalopathy with PNKD in a human with PIGN mutations." (PMID 35468813, 2022).
Hypotonia (3 papers, 2017 to 2025). Hypotonia is an abnormally low muscle tone (the amount of tension or resistance to movement in a muscle). "Mutations in the PIGN gene have been linked to multiple congenital anomalies-hypotonia-seizures syndrome 1 (MCAHS1)." (PMID 40099311, 2025). "Mutations in human PIGN have been associated with multiple congenital anomalies-hypotonia-seizures syndrome-1 (MCAHS1)." (PMID 27891564, 2017). "Mutations in PIGN, resulting in a glycosylphosphatidylinositol (GPI) anchor deficiency, typically leads to multiple congenital anomalies-hypotonia-seizures syndrome." (PMID 35468813, 2022).
leukemia (3 papers, 2017 to 2024). A malignant (clonal) hematologic disorder, involving hematopoietic stem cells and characterized by the presence of primitive or atypical myeloid or lymphoid cells in the bone marrow and the blood. "We also observed a similar PIGN expression aberration pattern in one (KG1) of two leukemia cell lines (KG1 and KG1a) originated from a single patient, KG1 harboring a myeloblast phenotype but KG1a bearing a stem/progenitor-like phenotype." (PMID 28187452, 2017). "We have previously examined the pathophysiological impacts of PIGN expression aberrations on leukemia progression, due to the role that GPI-APs play in the maintenance of cellular structure and protection, signal transduction, and enzymatic biological processes." (PMID 34561473, 2021).
acute myeloid leukemia (2 papers, 2017 to 2021). Acute myeloid leukemia (AML) is a group of neoplasms arising from precursor cells committed to the myeloid cell-line differentiation. "We linked PIGN gene expression aberrations to partial intron retentions between exons 14 and 15 that resulted in frameshifts and premature termination codons in a subset of myelodysplastic/acute myeloid leukemia (MDS/AML) patients." (PMID 34561473, 2021).
congenital diaphragmatic hernia (2 papers, 2018 to 2025). A posterolateral defect of the diaphragm that allows passage of abdominal viscera into the thorax, leading to respiratory insufficiency and persistent pulmonary hypertension with high mortality. "In particular, a lethal homozygous splicing defective variant in PIGN was identified in a fetus of syndromic congenital diaphragmatic hernia, which did not survive to birth mostly due to severe dysfunction of the protein." (PMID 29974678, 2018).
hyperphosphatasia (2 papers, 2017 to 2024). "In addition, for PIGN mutations, alkaline phosphatase testing is not informative as PIGN deficient individuals do not have hyperphosphatasia." (PMID 28327575, 2017).
multiple congenital anomalies-hypotonia-seizures syndrome 1 (2 papers, 2017 to 2020). "Biallelic variants in PIGN, have been recently associated with Multiple Congenital Anomalies-Hypotonia-Seizures syndrome 1 (MCAHS1; OMIM #614080) is an autosomal recessive disorder, and so is Fryns syndrome." (PMID 29096607, 2017).
myeloid leukemia (2 papers, 2017 to 2021). A clonal proliferation of myeloid cells and their precursors in the bone marrow, peripheral blood, and spleen. "RNAi-mediated suppression of PIGN in K562 myeloid leukemia cells caused MAD1 and MAD2 suppression but BUBR1 upregulation that was accompanied by an increase in the frequency of segregation errors." (PMID 34561473, 2021). "Moreover, MAD1, MAD2, and MPS1 were downregulated with PIGN loss in K562 myeloid leukemia cells." (PMID 34561473, 2021). "Conversely, CRISPR/Cas9-mediated PIGN ablation resulted in BUBR1 downregulation in the K562 myeloid leukemia cells." (PMID 34561473, 2021). "Overall, the progressive loss of PIGN protein expression in these leukemic cells and cell lines in the different MDS/leukemic progression phases indicated that PIGN loss may mark myeloid leukemia progression from a less aggressive disease state to a more aggressive one." (PMID 28187452, 2017).
absence seizures (1 paper, 2020). "In cases with PIGN-deficient, we expanded the types of atypical absence seizures, and described one patient with elevated serum ALP." (PMID 32220244, 2020).
Chorea (1 paper, 2025). Chorea (Greek for 'dance') refers to widespread arrhythmic involuntary movements of a forcible, jerky and restless fashion. "PIGN gene mutation is a rare autosomal recessive syndrome characterized by dysmorphic features and multiple congenital anomalies, along with severe neurological impairment, chorea, and seizures, ultimately leading to early death." (PMID 40099311, 2025).
colon cancer (1 paper, 2017). "Recently, a gene called Phosphatidylinositol Glycan Anchor Biosynthesis; Class N (PIGN), which is located at the 18q21.33 locus, was suggested as a cancer chromosomal instability (CIN) suppressor in a colon cancer model." (PMID 28187452, 2017).
colorectal cancer (1 paper, 2022). A primary or metastatic malignant neoplasm that affects the colon or rectum. "Of these, the PPM1D and PIGN genes have previously been identified as markers of colorectal cancer with a poor prognosis when highly expressed, whereas PLK2 has been described as a gene that promotes tumor growth in colorectal cancer." (PMID 35682850, 2022).
developmental and epileptic encephalopathy (1 paper, 2022). An epilepsy associated with developmental impairment that may be due to either the underlying etiology or the superimposed epileptic activity, or both. "This study reported a patient with PIGN mutation leading to developmental and epileptic encephalopathy and PNKD, to expand upon the genotype–phenotype correlation of PIGN." (PMID 35468813, 2022).
holoprosencephaly (1 paper, 2020). Holoprosencephaly (HPE) is a complex brain malformation resulting from incomplete cleavage of the prosencephalon, occurring between the 18th and 28th day of gestation, and affecting both the forebrain and face, which results in neurological manifestations and facial anomalies of variable severity. "Additionally, PIGN mutations in a mouse model result in a holoprosencephaly like phenotype." (PMID 33193741, 2020).
Hypsarrhythmia (1 paper, 2024). Hypsarrhythmia is abnormal interictal high amplitude waves and a background of irregular spikes. "Hypsarrhythmia was seen in five individuals (8.1%), three with variants in PIGA and two siblings with variants in PIGN." (PMID 38456468, 2024).
Intellectual disability (1 paper, 2021). "Biallelic PIGN variations should be considered as one of the causes of EIEE, especially when associated with seizures, hypotonia and intellectual disability." (PMID 34163418, 2021).
keloid (1 paper, 2024). An irregularly shaped, elevated mark on the skin caused by deposits of excessive amounts of collagen during wound healing. "Downregulation of the PIGN gene has been described in keloid fibroblasts after exposure to selenocysteine." (PMID 38534778, 2024).
cancer (7 papers, 2017 to 2025). A tumor composed of atypical neoplastic, often pleomorphic cells that invade other tissues. "For example, miRNAs such as MIR-181, MIR-30b, and MIR-200b as well as specific gene loci such as ADAMTS13, NOTCH4 and PIGN have been linked to many cancers, including EEC, and should be evaluated in vitro in the future." (PMID 30857319, 2019). "Highly expressed in normal prostate tissue with significant upregulation in tumour tissue (p-value < 0.001, GENT2 T-test), PIGN functions as a cancer chromosomal instability suppressor gene." (PMID 40064858, 2025). "PIGN has been reported to be a chromosomal instability suppressor in cancer whose silencing can lead to DNA replication stress and associated damage." (PMID 34412659, 2021).
tumor (5 papers, 2022 to 2025). "Biallelic PIGN loss is tentatively predicted in the tumour of the older aged presenting African patient." (PMID 40064858, 2025). "Notably, tumor-associated genes such as PLK2 and PIGN were among the DEGs activated specifically in cells producing the uS10 mutants." (PMID 35682850, 2022).
genetic diseases (3 papers, 2018 to 2025). "Phosphatidylinositol glycan anchor biosynthesis class N (PIGN) gene mutation is a rare autosomal recessive genetic disorder." (PMID 40099311, 2025).
neurodevelopmental disorder (1 paper, 2021). A behavioral and cognitive disorder with onset during the developmental period that involves impaired or aberrant development of intellectual, motor, or social functions. "PIGN is one of more than 20 genes in the phosphatidylinositol family involved in glycosylphosphatidylinositol (GPI) biosynthesis, which is associated with neurodevelopmental disorders (NDD)." (PMID 34163418, 2021).
PIGN also shares sentences with these, for which no sentence is quoted: diaphragmatic hernia (3 papers); infection (3); Cerebellar atrophy (2); Moebius syndrome (2); Nystagmus (2); acute lymphoblastic leukemia (1); angiosarcoma (1); brain malformations (1); cardiomyopathy (1); CHARGE syndrome (1); Dyskinesia (1); Edwards syndrome (1); Ellis-van Creveld syndrome (1); epilepsy syndrome (1); generalized seizures (1); heart failure (1); Hypokalemia (1); hypoxic-ischemic encephalopathy (1); Immunodeficiency (1); inflammation (1); Mabry syndrome (1); mammary carcinoma (1); meningitis (1); mitochondrial disease (1); movement disorder (1); Pachygyria (1); pulmonary fibrosis (1); Sepsis (1); septic shock (1); Shock (1).
A further 4 diseases each share a sentence with PIGN in 1 paper.